MYD88 (MYD88 innate immune signal transduction adaptor)
Diseases named in the same sentence as MYD88 in open-access papers (continued):
Sharing a sentence is not in itself a finding about the gene and the disease.
infection (continued). "In particular, MyD88-dependent TLRs are key receptors that can detect pathogen-derived LPS, flagellin or single-stranded RNA in the plasma membrane during infection with a variety of bacteria, such as Salmonella enteritidis and Escherichia coli." (PMID 32365080, 2020). "Since MyD88 is also a signal transducing molecule for the IL-18 receptor and the IL-1 receptor, the effects of these receptors on resistance to infection were studied." (PMID 32545735, 2020). "Our prior report demonstrated a critical role for MyD88-dependent signaling during S. aureus craniotomy infection, where MyD88 KO mice displayed heightened bacterial burden that translated into significant morbidity." (PMID 32290861, 2020). "When the planthoppers infected with RSV, the expressions of Toll and MyD88 were rapidly upregulated at the early stage (1 and 3 days post-infection), whereas Dorsal was upregulated at the late stage (9 days post-infection)." (PMID 33488623, 2020). "Because we observed that degradation of MyD88 during infection occurs in a proteasome-dependent manner, we next examined the physical interaction between MyD88 and SIAH1." (PMID 32117091, 2020). "These dynamic expressions of Toll, Tube, MyD88, and dorsal imply the active and complexed involvement of the canonical Toll signaling pathway in response to the infection process of RSV." (PMID 33488623, 2020). "As expected, viral titers collected from cells with intact MyD88 were 14- or 44-fold reduced in cells transfected with the SIAH1 siRNA or miR-424 mimic (respectively) prior to infection, as compared to control transfected cells." (PMID 32117091, 2020). "Intracellular infection also interferes with inflammatory pathways identified in our study, which are crucial for myeloid proliferation such as the MyD88-dependent signaling pathways the MAPK signaling and JAK2-STAT3 signaling." (PMID 33180876, 2020). "We found increasing amounts of IL-12p40 production as infection progressed in MyD88+/+ and MyD88-/- BMDM infected with RH compared to media control." (PMID 32413093, 2020). "At 24 h after infection, the titer was somewhat higher in MyD88 and Med31 RNAi flies than in mCherry RNAi control flies." (PMID 33746938, 2020). "Upon recognizing a PAMP, TLRs recruit downstream adaptors such as MyD88 to activate intracellular signaling pathways that result in the production of interferons and proinflammatory cytokines to antagonize the infection." (PMID 32365080, 2020). "TLR-7/9−/− (the double knockout mutant) or MyD88 mice made very little IFN-I in response to the yeast and mice lacking the IFN-γ receptor or TLR-7/9 were more susceptible to infection than controls as measured by survival and quantitative culture." (PMID 32545735, 2020). "CpG similarly provided protection in a model of intracerebral Escherichia coli, which implies that TLR-mediated resistance to infection is dependent on MyD88 signaling." (PMID 32547553, 2020). "For example, 80% of wild-type and Δdaisho flies survived for at least 7 days after infection with Botrytis cinerea, whereas >50% of MyD88− flies died after 2 days." (PMID 32038657, 2020). "The fact that craniotomy infections persist in the setting of normal MyD88 activity suggests that MyD88-dependent signals contribute to keeping bacterial expansion in check, but are not sufficient for clearing infection." (PMID 32290861, 2020). "T. gondii profilin is recognized by TLR 11/12, resulting in Myd88-dependent IL-12 production, a dominant mechanism driving IL-12 production in mice following intraperitoneal infection or oral infection." (PMID 33324583, 2020). "We therefore sought to determine if the antiviral effects of SIAH1 knockdown and miR-424 expression are a result of increased MyD88-dependent intracellular immune signaling during infection." (PMID 32117091, 2020). "Of great relevance to intestinal homeostasis, Myd88 is a crucial player in the interface between host and microbes and essential to host resistance to infection." (PMID 33414781, 2020).
infection (continued). "Inhibition of SIAH1 during infection results in increased innate immune signaling, but this increase, as well as inhibition of viral replication, is abrogated in cells in which the MyD88 gene has been deleted." (PMID 32117091, 2020). "Activated macrophages were preincubated with 0, 2.5, 5, 10 or 20 μg/mL of either MMG11 (TLR2 antagonist) or T6167923 (MyD88 inhibitor), followed by infection with MAP for 24 h." (PMID 33212859, 2020). "Activation of MyD88-NF-κB signaling leads to antimicrobial responses that promote resistance to infection by pathogens." (PMID 32365080, 2020). "Together, our results identify an alternative MyD88-independent pathway of IL-12p40 production triggered by Type I and Type II strains of Toxoplasma during both in vitro and in vivo infection." (PMID 32413093, 2020). "Our data demonstrate that GRA24 initiates a protective MyD88-independent immune response during in vivo infection." (PMID 32413093, 2020). "Compared with non-infected mice, mice submitted to S. pneumoniae stimulation expressed higher levels of Tlr2 and Myd88 mRNA at 24 h after infection in both the cortex and the hippocampus." (PMID 32676082, 2020). "The IL-18 receptor was demonstrated to mediate a critical upstream signal for the MyD88 signaling in T cells for the activation of a protective Th1 response during this infection." (PMID 32362926, 2020). "As observed in SARS-Cov-1 and MERS, IL-6 is generated early in the infection as a result of innate, MyD88-dependent pathway, immune receptor activation following the detection of viral proteins inside the infected cell." (PMID 32961074, 2020). "Infection of MyD88 knockout mice, in conjunction with vancomycin antibiotic treatment, has shown the ability to induce colonic pathology but failed to provoke overt diarrhea." (PMID 32637610, 2020). "In a vaccination model employing the uracil auxotrophic Toxoplasma strain cps1-1, we found that GRA24 drives an MyD88-independent Type I cytokine response associated with production of IFN-γ and protection from lethal challenge infection." (PMID 32413093, 2020). "More specifically, the expression of the adaptor molecule MyD88 is critical for the resistance to this infection in mice." (PMID 32362926, 2020). "MyD88+/+ and MyD88-/- mice were infected with WT alone or co-inoculated with WT and killed Tn5A7 that had been grown in kanamycin prior to infection." (PMID 32168364, 2020). "IL-1β is related to the resistance of the host to infection through stimulation of the IL-1 receptor and activation of the adapter protein MyD88, leading to the production of NO in macrophages." (PMID 32266161, 2020). "Immediately following infection, mycobacteria rely on PDIM to evade Myd88-dependent recruitment of microbicidal monocytes which can clear infection." (PMID 33226343, 2020). "Our prior work in a mouse model of S. aureus craniotomy infection revealed a critical role for myeloid differentiation factor 88 (MyD88) in bacterial containment and pro-inflammatory mediator production." (PMID 32290861, 2020). "While Toll-like receptor (TLR)/MyD88 signaling is important in mouse resistance to Toxoplasma, this pathway is likely less important in human infection." (PMID 32413093, 2020). "Deletion of the TLR7 adaptor, MyD88, also resulted in higher levels of FV infection in knockout (KO) mice compared with heterozygous controls, up to at least 16 weeks post-infection, and MyD88 KO mice were unable to generate FV-specific IgG responses." (PMID 32751803, 2020). "Strikingly, 3d mice also rapidly succumbed to infection, and their survival time was only slightly different from that of MyD88-defective animals." (PMID 32209688, 2020). "IL-6 is generated early in the infection as a result of innate, MyD88-dependent pathway, immune receptor activation by endogenous viral proteins." (PMID 32961074, 2020).
infection (continued). "The expressions of MyD88 and Toll were significantly increased after 1 and 3 days post-infection (dpi), whereas Tube was notably decreased after 1 dpi compare to that of the control (0 dpi)." (PMID 33488623, 2020). "CPE reduced the mRNA level of TLR4, MyD88, and AP-1 exerted anti-inflammatory effects, and simultaneously resistance LPS infection to stimulus." (PMID 32581806, 2020). "We also discovered that blocking macrophages during MAP infection with MyD88 antagonist significantly decreased response which illustrates the key role for MyD88 during infection." (PMID 33212859, 2020). "MiR‐148 is involved in the infection of V. harveyi by targeting MyD88 in many fish species to reduce the level of inflammation." (PMID 32940422, 2020). "Both with the reduced and the regular inoculum, myd88 mutants displayed a marked incapability to upregulate cxcl11aa, indicating that Myd88-dependent signaling is key to upregulate macrophage expression of cxcl11aa during Mm infection." (PMID 31110502, 2019). "In order to address the role of Mincle as well as the TLR adaptor protein Myd88 in the infection process of C. diphtheriae, in this study, a combination of BMM, Mincle- and MyD88-deficient cells were tested." (PMID 31057086, 2019). "M-MDSCs accumulated at the BCG infected site requires MyD88-dependent BCG-specific signals to evade the infection site." (PMID 31849990, 2019). "NMII spread systemically to all organs analyzed here and was detectable on day 7 after intratracheal infection by qPCR in decreasing quantity in liver, spleen and heart of Myd88+/−." (PMID 30800124, 2019). "The findings of a significant reduction of CCL2 and IL-6 in Myd88−/− mice in response to NMII infection are consistent with the observed reduction in leukocyte infiltration and granuloma response." (PMID 30800124, 2019). "H. felis infection up-regulated Cxcl13 expression in WT mice after 25 weeks of infection, while its expression was barely induced in MyD88−/− infected mice." (PMID 31065023, 2019). "Of the immune‐related molecules investigated, MyD88 mRNA expression was significantly upregulated in bone marrow at 24 hpi and in Harderian gland at both time points following infection with both NDVstrains (p < 0.05)." (PMID 30070070, 2019). "Expression of Ccl2 was induced on day 5 after NMII infection and showed a clear dependence on MyD88." (PMID 30800124, 2019). "As a result of the stimulation of IL-1R, IL-18R, and many TLRs, which are first lines defense against infection, the myeloid differentiation primary response 88 (MyD88) protein is the first adaptor protein that is connected to the receptors." (PMID 30997787, 2019). "While MyD88 contributes to the defense of neutrophils against P. gingivalis, pathogens can eliminate this host anti-infection mechanism by inducing the degradation of MyD88 in both humans and mice." (PMID 31380305, 2019). "Like fetuses born from WTinf, the progeny from heterozygous MyD88 pregnant mice (MyD88+/-inf) also presented reduced fetal weight upon infection." (PMID 30761111, 2019). "In contrast, high levels of Icam1 were detected in Myd88−/− mice infected with H. felis for 25 weeks that were reduced but still high at 47 weeks post-infection." (PMID 31065023, 2019). "Our data also show that infection of Myd88−/− mice with the attenuated NMII strain provides a model for prolonged and systemic infection with C. burnetii, facilitating in vivo studies of the host-C." (PMID 30800124, 2019). "Prior research has highlighted a prominent role for MyD88 and IL-1R signaling in the activation of immune responses that are necessary to control S. aureus infection in other animal models of infection." (PMID 30978245, 2019). "To better understand why Myd88−/− mice were more sensitive to lethality, we examined local and disseminated infection at 72 hpi." (PMID 30642901, 2019). "The infection induced expression of this chemokine is dependent on Myd88, the common adaptor of the majority of Tlrs, including tlr2." (PMID 31747871, 2019).
infection (continued). "H. felis infection led to activation of STAT3 in the stomach of WT and Myd88−/− mice after 25 and 47 weeks of infection." (PMID 31065023, 2019). "At the experimental endpoint (day 14 post-infection), surviving Myd88-/- mice not only had significantly elevated bacterial burdens in the infected femur, but also experienced more bacterial dissemination to the kidneys and liver." (PMID 30978245, 2019). "Since myd88 mutants display an increased infection level when infected with the same initial infection load as wild type controls, we compensated this with a reduced inoculum to obtain a similar infection level at 4 dpi." (PMID 31110502, 2019). "This indicates that the production of cytokines in the lungs is heavily dependent on MyD88 during the early stage of infection." (PMID 30642901, 2019). "Infection with H. felis led to Cxcl9 up-regulation only in Myd88−/− mice after 25 and 47 weeks of infection, while no induction was detected in WT animals." (PMID 31065023, 2019). "Together, these data demonstrate that the factors which activate lung neutrophils during RSV infection are present in the lungs of Myd88/Trif−/− mice despite the fact that these mice cannot recruit neutrophils to the lung during the infection." (PMID 31358860, 2019). "Accordingly, Myd88−/− × Trif−/− mice recovered the vascular barrier function in a comparable way to WT mice 4 days after infection." (PMID 30770250, 2019). "As expected, MyD88 knockdown decreased the expression of IM1 and Drosomycin upon infection, whereas cactus knockdown caused a strong induction of IM1 and Drosomycin expression also in the uninfected flies." (PMID 30633769, 2019). "In this context, while i.p. inoculation of BRD509E (at doses as low as 4 × 102 CFUs/mouse) resulted in high mortality rates in MyD88−/− mice, its oral administration led to the establishment of a chronic infection that lasted for more than 6 months." (PMID 29973931, 2018). "In contrast, MyD88−/− mice exhibited a persistent, progressively worsening infection accompanied by increasing levels of bacterial shedding over the 4-week observation period, reaching >105 CFUs/g feces." (PMID 29973931, 2018). "The finding that the B. thailandensis tssK-5 mutant is highly virulent in MyD88-/- mice indicates that the T6SS-5 is required to overcome MyD88-dependent immune responses to establish an infection." (PMID 30687298, 2018). "At 24 h p.i., the levels of RIG-I and MyD88 were significantly upregulated by infection with RRV-T48A534V compared to infection with RRV-T48." (PMID 30131356, 2018). "Louis, MO, USA) led a robust phosphorylated GSK3β and a moderately increased expression of TLR4 and MyD88 proteins but reduced the abundance of NF-κB and GSK3β proteins in U937-derived macrophage-like cells in response to the H37Rv infection." (PMID 30356420, 2018). "In contrast, MyD88−/− macrophages showed decreased levels of Arg1 and Nos2 transcripts in all infection periods analyzed (respectively)." (PMID 30555476, 2018). "Future work will need to evaluate the role of MyD88 in cardiomyocytes in other murine models of the acute infection where there is only a partial control of T. cruzi at the heart." (PMID 30067739, 2018). "First, we determined that changes in the expression of both miRNAs induced by infection were dependent on the adaptor molecule MyD88." (PMID 29942317, 2018). "Compared to WT macrophages, the level of the Cat2B transcript was increased in MyD88−/− macrophages 48 h after infection and increased levels of the Cat1 transcript were observed in MyD88−/− macrophages 4, 24, and 48 h after infection (respectively)." (PMID 30555476, 2018). "Here, we reported the roles of TLR2, TLR4, and the adaptor molecule MyD88 in mediating the phagocytosis of L. amazonensis and conferring resistance to infection, in contrast to the higher infectivity index observed in the absence of those molecules." (PMID 30555476, 2018).
infection (continued). "No significant levels of autoreactive antibodies were detectable in wild-type (MyD88+/+) mice before or after infection." (PMID 29973931, 2018). "Its overexpression in macrophages has been linked to a significant decrease in MyD88 protein expression, as well as a reduced production of inflammatory mediators such as NF-κB, TNF-α, and IL-6 in response to infection or LPS stimulation." (PMID 29988529, 2018). "Infection of Myd88-/- BMDCs significantly reduced the release of PTX3 with respect to wild-type BMDCs." (PMID 30532257, 2018). "Allelic variants of the genes MYD88 and LY96 associated with a lower risk of infection were more frequent in this group." (PMID 29940023, 2018). "The miR-124 expression is enhanced in the peripheral leukocytes of patients with pulmonary tuberculosis, and MyD88 overexpression and/or infection induce its expression in vitro." (PMID 29988529, 2018). "More recently, it was reported that mice with an IEC-specific deletion of MyD88 display defects in Muc2 expression and crypt antimicrobial capacity in the cecum during the early phase of infection with C. rodentium." (PMID 28520792, 2017). "In order to assess the cell type-specific impact of MyD88 signaling on the induction of innate and adaptive immune responses after infection, we used a genetic approach that allows the expression of functional MyD88 in Cre-expressing MNP subsets." (PMID 28520792, 2017). "The MyD88 (myeloid differentiation primary response gene 88) signalling network plays a central role in defence against infection by pathogens." (PMID 28512203, 2017). "We detected increased expression of pro-inflammatory KC (protein and mRNA) and Il6 (mRNA) in WT BMMs and to a significantly lesser extent also in MyD88-/- cells at 24 h post infection (p.i.)." (PMID 28445535, 2017). "Unlike HeLa and HEK293 cells lines, we noted that primary mouse fibroblasts display MyD88-dependent NF-κB activation even upon infection with the EPEC escV mutant." (PMID 28671993, 2017). "Comparing the number of upregulated genes between Myd88−/− and WT at 47 weeks post infection, there were more upregulated genes (1140) in Myd88−/− mice compared to WT mice (189 genes)." (PMID 28201999, 2017). "In the current study, we did not detect significant differences in the level of AIM2 mRNA expression between IOE-infected WT and MyD88-/- mice at late stages of infection (day 7 p.i.)." (PMID 29049365, 2017). "Primary anti-DenV2 sera obtained from TLR2 KO and MyD88 KO mice showed lower fold of infection enhancement than those from BL/6 mice." (PMID 29285314, 2017). "As ILC3 and ILC3-derived cytokines are known to have a prominent role in host protection during the early innate phase of infection, we next assessed the impact of CD11c/LysM-directed MyD88 reactivation on the ILC3 response." (PMID 28520792, 2017). "TLR2-dependent osteoclast differentiation and bone resorption in response to infection with S. aureus and B. abortus were also shown to be MyD88 dependent." (PMID 28848717, 2017). "In accordance with S. suis-induced IFN-β production by DCs being mostly MyD88-dependent, the TLR3, which is MyD88-independent and recruits TRIF, was only minimally implicated, and only following infection with the SLY-negative ST25 strain 89-1591 (p < 0.05)." (PMID 28894449, 2017). "Nuclear translocation of IRF-1 was markedly reduced over the first 3 days of infection in macrophages treated with siRNA to MyD88, suggesting MyD88 is conveying Mav-induced responses from the LAMP1+ phagolysosome." (PMID 28806745, 2017). "It is thus possible to unambiguously dissect the direct impact of functional MyD88-mediated signaling in specific cell types, and to determine the consequences for the activation of the different processes of the host response upon infection." (PMID 28520792, 2017). "Numerous myd88 DEGs (37 in total) were downregulated throughout the infection stages, with only one DEG at 24 h pi and 72 h pi respectively found to be upregulated." (PMID 28871168, 2017).